PABPN1L (PABPN1 like, cytoplasmic)
Description:
Binds the poly(A) tail of mRNA.
Synonyms: ePABP2; PABPNL1
Tractability: PROTAC: ubiquitination databases record sites on it.
Gene: Protein-coding gene on chromosome 16 (88,863,333 to 88,866,660, reverse strand). Ensembl gene ENSG00000205022.
Subcellular location: Cytoplasm
Pathways (Reactome):
Developmental Biology: M-decay: degradation of maternal mRNAs by maternally stored factors
Gene Ontology:
Molecular function: nucleic acid binding; poly(A) binding; RNA binding
Biological process: nuclear-transcribed mRNA catabolic process, deadenylation-dependent decay
Cellular component: cytoplasm
Genetic constraint (gnomAD): Loss-of-function variants: 46 observed, 31.7 expected, observed/expected ratio (o/e) 1.45, 90% interval 1.14 to 1.83. The synonymous counts are far from expectation, so gnomAD's model fits this gene poorly and the ratio says little. Missense variants: 459 observed, 318.12 expected, observed/expected ratio (o/e) 1.44, 90% interval 1.34 to 1.56. Synonymous variants: 182 observed, 131.77 expected, observed/expected ratio (o/e) 1.38, 90% interval 1.22 to 1.56.
Homologues: Orthologues: chimpanzee PABPN1L (98% identical), macaque PABPN1L (94% identical), guinea pig PABPN1L (69% identical), rat Pabpn1l (68% identical), mouse Pabpn1l (66% identical), pig PABPN1L (63% identical), tropical clawed frog pabpn1l (37% identical). Paralogues in human: PABPN1 (43% identical).
Diseases named in the same sentence as PABPN1L in open-access papers:
PABPN1L is named in the same sentence as 3 diseases in open-access papers, as found by Europe PMC text mining. Sharing a sentence is not in itself a finding about the gene and the disease. The quoted sentences say what the papers report.
female infertility (1 paper, 2023). Diminished or absent ability of a female to achieve conception. "Impediment in maternal RNA clearance by genetic inactivation of the RNA degradation-associated genes Btg4, Pabpn1l, or Cnot6l leads to MZT failure and female infertility in mice." (PMID 37025171, 2023). "Embryos with either BTG4 or PABPN1L depletion will be arrested at the 1∼2-cell stage and characterized by female infertility." (PMID 37025171, 2023).
Infertility (1 paper, 2015). "In order to verify the practicability of our tool, we applied DeAnnCNV to a study of infertile men and found that two patients have a CNV (each patient has only one of the two copies), which shares a gene PABPN1L, hemizygous deletion of which causes male infertility in mice." (PMID 26013811, 2015). "Interestingly, by searching for ‘infertility’ in the ‘MGI-KO’ column, we found that two patients, patients 3 and 4, carried two CNVs (copy number = 1) that shared a gene PABPN1L, localized at human 16q24.3." (PMID 26013811, 2015).
male infertility (1 paper, 2015). The inability of the male to effect fertilization of an ovum after a specified period of unprotected intercourse. "Taken together, these results indicated that loss of a copy of PABPN1L is the most probable cause of male infertility in these two patients, although functional research on how haploinsufficiency in PABPN1L results in male infertility is needed." (PMID 26013811, 2015).